CPT1B (carnitine palmitoyltransferase 1B)
Diseases named in the same sentence as CPT1B in open-access papers (continued):
Sharing a sentence is not in itself a finding about the gene and the disease.
cardiac hypertrophy (13 papers, 2017 to 2025). "Long-term CPT1B inhibition can cause lipotoxicity in the heart under pathological stress, leading to more cardiomyocyte apoptosis and exacerbation of cardiac hypertrophy." (PMID 36817129, 2023). "Moreover, CPT1b overexpression decreased L-carnitine levels and inhibited the Jak2/Stat3 signaling pathway, which was associated with the pathogenesis of myocardial hypertrophy." (PMID 40093901, 2025). "Moreover, CPT-1B deficiency triggered lipotoxicity in the cardiac cells under stress, causing worsening of cardiac pathology and inducing cardiac hypertrophy as well as mortality in mice." (PMID 38652282, 2024). "Similarly, conditional deletion of Cpt1b in skeletal and cardiac muscle caused massive cardiac hypertrophy and reduced survival due to the development of congestive heart failure, but cardiac fibrosis was not assessed in these mice." (PMID 36742465, 2023). "In vivo studies were conducted to evaluate the roles of CHACR and CPT1b in pathological cardiac hypertrophy." (PMID 40093901, 2025). "Our findings indicate that CHACR mitigated cardiac hypertrophy by regulating the expression of carnitine palmitoyltransferase-1b (CPT1b) protein." (PMID 40093901, 2025). "On this foundation, we proved that CPT1b suppressed Jak2/Stat3 signaling pathway to aggravate cardiac hypertrophy." (PMID 40093901, 2025). "In this study, we found that CHACR interacted with CPT1b and protected it from proteasomal degradation by reducing its ubiquitination level in cardiomyocytes, thus alleviating cardiac hypertrophy." (PMID 40093901, 2025). "CHACR can attenuate cardiac hypertrophy through upregulating carnitine palmitoyltransferase-1b (CPT1b) expression." (PMID 40093901, 2025). "CHACR, which was mainly expressed in the cytoplasm, bound directly to CPT1b and upregulated its expression, which consequently inhibited L-carnitine level to inactivate the Jak2/Stat3 pathway, thereby attenuating cardiac hypertrophy (Graphical abstract)." (PMID 40093901, 2025). "Our findings suggested that CHACR inhibited cardiac hypertrophy in mice by binding to and regulating the expression of CPT1b protein." (PMID 40093901, 2025). "The present study demonstrated that the novel circRNA CHACR suppressed cardiac hypertrophy by facilitating the protein expression of CPT1b." (PMID 40093901, 2025). "Heterozygous Cpt1b knockout mice develop cardiac hypertrophy, increased fibrosis, and die within two weeks following transverse aortic constriction." (PMID 36742465, 2023). "Altogether, these data illustrate that FABP3 participates in cardiac hypertrophy by synergistically activating Mlycd and Cpt1b and repressing Gck and Acaca via PPARα." (PMID 34458345, 2021). "LncRNA uc.323 also regulates the expression of the cardiac hypertrophy-related gene, carnitine palmitoyltransferase 1b (Cpt1b), through direct interaction with EZH2." (PMID 33802186, 2021). "Oxfenicine inhibits Cpt1b more selectively, but we have shown that ablation of Cpt1b in heart leads to cardiac hypertrophy and increased mortality." (PMID 29240830, 2017). "In addition, the inhibition of CPT1b expression aggravated myocardial hypertrophy in TAC mice with overexpression of CHACR." (PMID 40093901, 2025). "CHACR attenuated cardiac hypertrophy by increasing the expression of CPT1b, which is involved in regulation of the Jak2/Stat3 pathway, demonstrating the participation of this circRNA-mediated protein mechanism in the pathogenesis of cardiac hypertrophy." (PMID 40093901, 2025). "In addition, CHACR or CPT1b overexpression alone in mice subjected TAC reduced cardiac hypertrophy compared to TAC+NC group." (PMID 40093901, 2025). "Cpt1b (carnitine O-palmitoyltransferase 1, muscle isoform) has an enrichment score of 3 with high PSM counts and its deficiency in mouse exacerbates pressure overload-induced cardiac hypertrophy and heart failure." (PMID 34200203, 2021).
cardiac hypertrophy (continued). "Interestingly heterozygous CPT1b knockout mice were more prone to cardiac hypertrophy and exhibited mitochondrial abnormalities and ceramide accumulation, leading to cardiomyocyte apoptosis." (PMID 32110930, 2020). "Furthermore, CHACR inhibited the Jak2/Stat3 pathway by regulating CPT1b expression, which may be involved in the pathogenesis of cardiac hypertrophy." (PMID 40093901, 2025). "It was then hypothesized that CHACR regulated cardiac hypertrophy through CPT1b." (PMID 40093901, 2025).
prostate carcinoma (11 papers, 2015 to 2024). A carcinoma that arises from epithelial cells of the prostate gland. "The upregulation of Carnitine Palmitoyltransferase 1B (CPT1B) has been identified as a prognostic marker in prostate cancer, with higher levels of expression linked to poorer patient outcomes." (PMID 38383657, 2024). "CPT1B, a rate-limiting step in the catalytic oxidation of fatty acids, is upregulated in prostate cancer and is associated with poor prognosis." (PMID 34970420, 2021). "Upregulation of CPT1B is correlated with poor prognosis in prostate cancer and overexpression of CPT1B promotes the resistance of C4-2R cells to enzalutamide." (PMID 37221577, 2023). "It regulated the differentially expressed gene carnitine palmitoyltransferase 1A (CPT1A) and its homolog CPT1B, shown to regulate prostate cancer growth under hypoxic conditions." (PMID 36064320, 2022). "Further study revealed that AR-mediated CPT1B promoted castration-sensitive and castration‐resistant prostate cancer (CRPC) progression by upregulating AKT expression and phosphorylation." (PMID 34706720, 2021). "Also, CPT1B was reported to be upregulated in prostate cancer and correlated with poor prognosis, in support of our findings." (PMID 36778142, 2023). "CPT1B overexpression is correlated with poor prognosis in prostate cancer." (PMID 34181336, 2021). "Overexpression of CPT1B was correlated with worse OS in prostate cancer." (PMID 34706720, 2021). "Gene expression analysis showed that in more than 50% of the prostate cancer patient samples CPT1B enzyme mRNA, a rate limiting enzyme involved in the β-oxidation of FA, was elevated and proposed that FAO is a prominent oncobioenergetic pathway in prostate cancer." (PMID 26515588, 2015).
narcolepsy (10 papers, 2009 to 2024). A sleep disorder characterized by a tendency for excessive sleepiness during the day which occurs even after adequate sleep in the nighttime. "The new narcolepsy-susceptibility region, CPT1B/CHKB, was discovered through a GWAS performed to search for genetic factors other than the established factor, HLA." (PMID 24705288, 2014). "SNP rs5770917 adjacent to the gene encoding CPT1B has been found to be associated with narcolepsy." (PMID 23349733, 2013). "Besides the CRAT association in our study, interestingly, a recent GWAS for narcolepsy with cataplexy in a Japanese population identified a significant association between a SNP adjacent to CPT1B (carnitine palmitoyltransferase 1B)." (PMID 23646285, 2013). "A genome-wide association study (GWAS) identified a novel narcolepsy-related single nucleotide polymorphism (SNP), which is located adjacent to the carnitine palmitoyltransferase 1B (CPT1B) gene encoding an enzyme involved in β-oxidation of long-chain fatty acids." (PMID 23349733, 2013). "As a result, an SNP located between CPT1B and CHKB on Chromosome 22 was found to be associated with narcolepsy." (PMID 24705288, 2014). "In a previous study, we analyzed the expression level of CPT1B and measured the carnitine fractions in blood samples obtained from narcolepsy patients and healthy control subjects." (PMID 23349733, 2013). "CPT1B, CHKB and HLA are candidates for susceptibility to CNS hypersomnias (EHS), as well as narcolepsy with cataplexy." (PMID 19404393, 2009). "SNP rs5770917 located between CPT1B and CHKB, and HLA-DRB1*1501-DQB1*0602 haplotype were previously identified as susceptibility loci for narcolepsy with cataplexy." (PMID 19404393, 2009). "In cohort studies in Japan and South Korea, GWAS was used to identify a non-HLA-related variant located between CHKB and CPT1B that is significantly associated with narcolepsy." (PMID 38725645, 2024). "Other studies revealed that the diagnosis of narcolepsy but not CPT1B expression level was associated with abnormally and significantly low acylcarnitine levels." (PMID 26722632, 2015). "In contrast, CPT1B and CHKB, which are reportedly associated with narcolepsy with cataplexy in a Japanese population, are also reportedly associated with both HLA-DQB1*06:02-positive EHS and EHS in patients lacking HLA-DQB1*06:02 (designated here as HLA-DQB1*06:02-negative EHS)." (PMID 23646285, 2013). "Thus, either of these two genes (CPT1B and CHKB) is a plausible candidate for susceptibility to CNS hypersomnias (EHS), as well as narcolepsy with cataplexy." (PMID 19404393, 2009). "CPT1B expression was significantly higher in the narcolepsy patients than in the controls, and acylcarnitine levels were abnormally low in 21% of the narcolepsy patients while those of all the controls were within the normal range, suggesting that fatty acid β-oxidation is altered in narcolepsy." (PMID 23349733, 2013).
bladder cancer (7 papers, 2019 to 2025). "Studies have found the downregulation of CPT1B can cause fatty acid β‐oxidation impairment and play an important role in the high‐grade progression of bladder cancer." (PMID 35681277, 2023). "It was shown that the expression of CPT1B was downregulated in bladder cancer tissues together with other genes in the carnitine–acylcarnitine metabolic pathway." (PMID 31212967, 2019). "However, confusingly, some studies have found that the down-regulation of FAO-related protein CPT1B contributes to high-grade bladder cancer, vice versa, overexpression of CPT1B in high-grade bladder cancer cells can reduce EMT in vitro, and diminish cell proliferation, EMT and metastasis in vivo." (PMID 40290117, 2025). "For example, low expression of CPT1B in high-grade muscular invasive bladder cancer (MIBC), and ectopic high expression of CPT1B can increase FAO and impede the proliferation and colonization and metastasis of bladder cancer cells." (PMID 39596847, 2024).
heart failure (7 papers, 2015 to 2025). Inability of the heart to pump blood at an adequate rate to meet tissue metabolic requirements. "Down-regulation of CPT1B activity has been associated with heart failure in patients and various experimental models, indicating an important role in metabolic remodeling." (PMID 40646338, 2025). "Meanwhile, loss of CPT1B activity in the heart increases myocardial lipids in obese mice and causes cardiac lipotoxicity in a heart failure mouse model." (PMID 37275238, 2023). "For example, scRNA-seq has revealed a shift from fatty acid oxidation to glycolysis in cardiomyocytes during heart failure, with changes in key enzymes such as CPT1B and PDK4 affecting circulating metabolite levels (e.g., lactate, acylcarnitines)." (PMID 41403700, 2025). "As cardiac metabolism shifts from fatty acid oxidation to glycolysis during heart failure, Cpt1b-targeted therapy was used as a therapeutic approach in inhibiting fatty acid oxidation to treat heart failure." (PMID 34200203, 2021). "In summary, cardiac PHB2 deficiency-induced mitochondrial dysfunction resulted in fatty acid metabolic disorder through downregulating CPT1b, which played a major role in the course of heart failure in Phb2 cKO mice." (PMID 32165613, 2020). "The ablation of cardiac PHB2 exhibits a more severe heart failure at an early age (50% mortality at day 70); however, haploinsufficiency of CPT1b mice showed heart failure only under a severe pressure-overload condition." (PMID 32165613, 2020). "Upregulation of CPT1B expression might therefore represent a promising approach to treat or prevent heart failure." (PMID 40646338, 2025). "A reduction in total PHB2 expression in cardiac-specific PHB2 knockout mice impairs myocardial fatty acid oxidation (FAO) and induces heart failure through suppressing carnitine palmitoyltransferase 1b (CPT1b), a rate-limiting enzyme of cardiac mitochondrial FAO." (PMID 38856931, 2024). "Therefore, we aimed to investigate whether CPT1B overexpression could play a therapeutic role in heart failure." (PMID 40646338, 2025). "Thus, our study indicated that CPT1b might be a potential therapeutic target for heart failure." (PMID 32165613, 2020). "Reductions in both CPT1b and GLUT4 have been shown to promote pathological hypertrophy and heart failure." (PMID 26064889, 2015).
diabetes (6 papers, 2012 to 2023). "At E10.5, effects of diabetes were significant for Slc27a6/Fatp6, Slc27a4/Fatp4, and Cpt2 (27.8%, 19.4%, and 19.7%, respectively), and for Cpt1a, Slc2a13/Glut13, and Cpt1b, diet was a significant contributor (42.9%, 38.7%, and 31%, respectively)." (PMID 31774824, 2019). "Taken together, these results suggested that treatment with GCGR mAb could effectively attenuate the diabetes‐induced upregulation of CPT1B, OPA1, and MFN1, and oxidative stress in CMECs." (PMID 37596940, 2023). "Specifically, methylation changes occurs in genes related to intermediate metabolism, diabetes, inflammation, and signal transduction process, such as CPT1B and GNAS, which are specifically involved in acyl-carnitine process in mitochondria, and glucose and energy regulation, respectively." (PMID 29295516, 2017).
Hepatic steatosis (6 papers, 2019 to 2025). Steatosis is a term used to denote lipid accumulation within hepatocytes. "Interestingly, studies have shown that CPT1B affects lipid metabolism in Chinese Simmental cattle and that the expression of CPT1B is associated with preventing fatty liver disease." (PMID 35011132, 2021). "CPT-1b is responsible for catalyzing hepatic mitochondrial β-oxidation to ameliorate hepatic steatosis." (PMID 37764698, 2023). "In this study, the injection of HFD-induced obese mice with MS-275 prevented hepatic steatosis by reducing de novo lipogenesis and increasing lipolysis and mitochondrial oxidation, by increasing the expression of oxidation-related genes, such as PPARα, MCAD, CPT1b, and FGF21." (PMID 36077368, 2022).
breast tumor (4 papers, 2019 to 2025). "Previous reports have highlighted that STAT3 in breast tumor-associated CD8+ effector T cells promote FAO activity by upregulating CPT1B." (PMID 40612678, 2025). "Among the various metastatic genes identified, elevated expression of CPT1B is reported in chemoresistant metastatic breast tumors." (PMID 34181336, 2021).
ovarian carcinoma (4 papers, 2016 to 2025). A malignant neoplasm originating from the surface ovarian epithelium. "The death of these adipocytes causes the release of free fatty acids, which are taken up by ovarian cancer cells and cause an upregulation of acetylated STAT3 and carnitine palmitoyltransferase 1B (CPT1B)." (PMID 39802952, 2024). "In contrast, expression of CPT1B protein was absent in ovarian cancer cell lines." (PMID 26716645, 2016).
steatosis (4 papers, 2017 to 2024). Increased lipid within the cytoplasm of cells. "Enhancing FAO via LCA supplementation (the cofactor of CPT1B), attenuated cardiac steatosis and lipotoxicity-induced pathological changes in the atria of obese mice, resulting in restored AF substrates and ameliorated AF susceptibility." (PMID 34899326, 2021). "Genes involved in steatosis (Cd36, Lpl), hepatoxicity (Avpr1a, Pla2g12a), necrosis (Serpine1), fatty acid metabolism (Acox1, Cpt1b, Cyp4a10, Ehhadh), lipid transport (Apoa1), and PPAR transcription factors (Pparδ) were altered with PFHpS exposure compared to vehicle-exposed animals." (PMID 39066581, 2024).
metabolic syndrome (3 papers, 2013 to 2021). A cluster of metabolic risk factors for CARDIOVASCULAR DISEASES and TYPE 2 DIABETES MELLITUS. "Also, a common haplotype of CPT1B has been associated with the metabolic syndrome in male participants." (PMID 33639916, 2021). "Finally, CPT1B with 12 CpGs in the DMP and BH-DMP lists, is a carnitine palmitoyltransferase specifically expressed in mitochondria of skeletal muscle and associated with metabolic syndrome and lipid deposition." (PMID 24373378, 2013).
cardiomyopathy (2 papers, 2024 to 2026). A disease of the heart muscle or myocardium proper. "Consistently, in vivo cardiac-specific overexpression of CPT1B via an AAV9 vector with a cardiomyocyte-specific promoter (cTnT) also confirmed that the K321-R mutation of CPT1B protected against endotoxic shock-induced secondary cardiomyopathy." (PMID 42209697, 2026). "E2 and 2ME abrogate DOX-induced cardiomyopathy partly through modulation of GLUT 4 and CPT-1B enzymes." (PMID 38652282, 2024). "Our results displayed that co-treatment of E2 and/or 2ME with DOX significantly reduced DOX-induced cardiomyopathy and enhanced the metabolism of the heart through the maintenance of GLUT4 and CPT-1B enzymes." (PMID 38652282, 2024).
Cataplexy (2 papers, 2009 to 2013). A sudden and transient episode of bilateral loss of muscle tone, often triggered by emotions. "Thus, SNP rs5770917 located between CPT1B and CHKB might be involved in the pathogenesis of excessive daytime sleepiness, not cataplexy." (PMID 19404393, 2009).
fatty acid metabolic disorder (2 papers, 2020 to 2022). "In heart cells, knocking out PHB2 can cause carnitine palmitoyl transferase 1b (CPT1b) to induce cardiac fatty acid metabolism disorders." (PMID 36348375, 2022).
hepatocellular carcinoma (2 papers, 2025). A malignant tumor that arises from hepatocytes. "In hepatocellular carcinoma, particularly during cachexia, CPT1B dysregulation exacerbates metabolic imbalance." (PMID 41219902, 2025). "This approach may allow selective targeting of CPT1A-rich hepatocellular carcinoma cells or CPT1B-rich cardiomyocytes while minimizing off-target toxicity." (PMID 41219902, 2025). "As a reversible inhibitor that targets both CPT1A and CPT1B, perhexiline maintains anti-cancer efficacy while demonstrating reduced cardiotoxicity in preclinical chronic lymphocytic leukemia (CLL) and hepatocellular carcinoma (HCC)." (PMID 40867868, 2025).
acute myeloid leukemia (1 paper, 2024). Acute myeloid leukemia (AML) is a group of neoplasms arising from precursor cells committed to the myeloid cell-line differentiation. "In high-grade invasive bladder cancer and acute myeloid leukemia, the protein level of CPT1B in cancer tissues is lower than that of adjacent cancer and can promote the malignant biological behavior of cancer cells and prolong the survival of patients." (PMID 39596847, 2024). "In contrast, a study of 324 patients with acute myeloid leukemia (AML) found that CPT1B was significantly higher in AML patients than in the general population, and 324 clinical patient cases showed that this result often indicated shorter survival." (PMID 39596847, 2024).
behavioural disorders (1 paper, 2017). "Moreover, CPT1B has been recently associated with behavioural disorders characterizing post-traumatic stress both in human and rodent models, and ACSBG1 participate in myelinogenesis." (PMID 29020091, 2017).
bladder tumors (1 paper, 2021). "Although high expression of CPT1A significantly correlated with poor patients’ survival, CPT1B transcripts have been reported to be downregulated in high grade bladder tumors and positively associated with patients’ survival." (PMID 34764423, 2021).
cholestasis (1 paper, 2017). Impairment of the bile flow caused by obstruction within the liver, or outside the liver in the bile duct system. "Quantitative real-time PCR (QPCR) analysis indicated the inhibition of Cpt1b, Cpt2, Mcad and Hadha in cholestasis was increased by fenofibrate (P < 0.01)." (PMID 28855630, 2017).